ZNF493 (zinc finger protein 493)
Description:
May be involved in transcriptional regulation.
Synonyms: FLJ36504
Tractability: PROTAC: ubiquitination databases record sites on it.
Gene: Protein-coding gene on chromosome 19 (21,397,119 to 21,427,577, forward strand). Ensembl gene ENSG00000196268.
Subcellular location: Nucleus
Pathways (Reactome):
Gene expression (Transcription): Generic Transcription Pathway
Gene Ontology:
Molecular function: transcription cis-regulatory region binding; DNA-binding transcription repressor activity, RNA polymerase II-specific
Biological process: regulation of transcription by RNA polymerase II; negative regulation of transcription by RNA polymerase II
Cellular component: nucleus
Genetic constraint (gnomAD): Loss-of-function variants: 11 observed, 12.32 expected, observed/expected ratio (o/e) 0.89, 90% interval 0.56 to 1.47. The upper end of that interval is the gene's LOEUF score, 1.47, which puts it in group 6 of 6, group 1 being the genes least tolerant of losing a copy. Missense variants: 944 observed, 909.62 expected, observed/expected ratio (o/e) 1.04, 90% interval 0.98 to 1.1. Synonymous variants: 282 observed, 293.85 expected, observed/expected ratio (o/e) 0.96, 90% interval 0.87 to 1.06.
Homologues: Orthologues: chimpanzee ZNF493 (89% identical), macaque ZNF493 (85% identical). Paralogues in human: ZNF595 (54% identical), ZNF254 (52% identical), ZNF85 (52% identical), ZNF726 (51% identical), ZNF708 (51% identical), ZNF724 (51% identical), ZNF429 (50% identical), ZNF728 (50% identical), ZNF43 (49% identical), ZNF681 (48% identical), ZNF732 (47% identical), ZNF93 (47% identical), and 164 more.
Diseases named in the same sentence as ZNF493 in open-access papers:
ZNF493 is named in the same sentence as 6 diseases in open-access papers, as found by Europe PMC text mining. Sharing a sentence is not in itself a finding about the gene and the disease. The quoted sentences say what the papers report.
Sepsis (2 papers, 2021 to 2022). Sepsis is defined as life-threatening organ dysfunction caused by a dysregulated host response to infection. "Studies uncovered that the ribosome-related genes TLCD4, PRSS30P, and ZNF493 had a moderate performance to identify sepsis-induced acute respiratory distress syndrome (ARDS) in sepsis patients." (PMID 36299685, 2022). "Feature selection analysis revealed that three genes, TLCD4, PRSS30P, and ZNF493, showed moderate performance in identifying sepsis-induced ARDS from sepsis." (PMID 33818300, 2021). "Three genes–TLCD4, PRSS30P, and ZNF493 indicated moderate performance in distinguishing sepsis-induced ARDS from sepsis." (PMID 33818300, 2021). "We performed feature selection analysis and found that combination of three genes (TLCD4, PRSS30P, and ZNF493) and seven genes (TLCD4, PRSS30P, ZNF493, AGO2, SLC37A3, SLC2A1, and RPL11) showed moderate performance in identifying patients with sepsis and ARDS within 1 day after admission." (PMID 33818300, 2021).
colorectal cancer (1 paper, 2024). A primary or metastatic malignant neoplasm that affects the colon or rectum. "ZNF493 (zinc finger protein 493) was reported to be frequently mutated in colorectal cancer." (PMID 39548061, 2024).
infection (1 paper, 2012). The state of being infected such as from the introduction of a foreign agent such as serum, vaccine, antigenic substance or organism. "The role for ZNF493-related epigenetic regulation of TLRs in the response to infection with S. enteritidis, however, seems to be quite different from the basic negative regulatory mechanism of the TLR signaling pathway." (PMID 22438967, 2012).
tumour (1 paper, 2019). "Of note, ZNF3, ZNF257, ZNF479 and ZNF493, which were found to be mutated in the PanTT26 tumour, also appeared to be mutated in the PanTT39 tumour specimen." (PMID 30377343, 2019).
ZNF493 also shares sentences with these, for which no sentence is quoted: acute respiratory distress syndrome (1 paper); lung adenocarcinoma (1).